G6PD (glucose-6-phosphate dehydrogenase)
Diseases named in the same sentence as G6PD in open-access papers (continued):
Sharing a sentence is not in itself a finding about the gene and the disease.
malaria (continued). "Glucose-6-phosphate dehydrogenase (G6PD) deficiency is the most common human enzyme disorder worldwide, occurring more frequently in malaria-endemic areas." (PMID 36431166, 2022). "Among 1106 notification forms with a “source of G6PD information” field filled out, there were 61 occasions when the G6PD value on the card was used to inform treatment when the patient presented again with malaria." (PMID 36422580, 2022). "Overall an individual’s G6PD activity was 10% greater when measured during an acute episode of malaria compared to when remeasured during follow up." (PMID 35544453, 2022). "For screening purposes, a finger-prick blood sample will be collected and used for malaria slide, Hb measurement and G6PD testing using the Biosensor." (PMID 35585641, 2022). "Our study highlights that G6PD activity in the same individual can differ significantly when measured during acute presentation with malaria and after recovery." (PMID 35544453, 2022). "National malaria programme staff outlined how a new treatment regimen, namely tafenoquine, and quantitative G6PD testing, were needed to address low adherence among P. vivax cases and to ensure proper prescription of the regimen." (PMID 35164759, 2022). "This is possibly due to the small number of patients enrolled, which limit the chance to detect haemolytic anaemia in malaria patients carrying G6PD AuresT143C, G6PD ViangchanG871A and G6PD KaipingG1388A." (PMID 36038921, 2022). "As such, polymorphisms in G6PD, MBL2, TNF-α, and NOS2 genes in a group of P. falciparum-infected and P. falciparum-uninfected adults and children living in a low and a high malaria transmission setting in Ghana were characterized." (PMID 35291755, 2022). "The G6PD and HBB deficiencies are widespread in West Africa endemic malaria regions such as The Gambia, Mali, and Burkina Faso." (PMID 35811813, 2022). "More data on G6PD and HBB polymorphisms and their incidence on malaria outcome and corresponding haematological parameters are essential for different malaria eradication strategies in endemic West African countries." (PMID 35811813, 2022). "Participants categorized by G6PD status during acute malaria and follow up stratified by species and site." (PMID 35544453, 2022). "With the multitude of barriers to attend health centres it is critical to build the capacities of village-based community health workers to diagnose malaria, assess G6PD status reliably, and provide radical cure under the supervision of health centres." (PMID 36195916, 2022). "However, in practice, the G6PD status of patients is often unknown at the time of malaria diagnosis due to the price and complexity of the available diagnostic products—especially in the context of malaria-endemic and low-resource settings." (PMID 34383774, 2021). "Brazil’s recently revised malaria treatment guidelines (2020) recommend that patients with P. vivax malaria be tested for G6PD status prior to primaquine administration, if testing is available." (PMID 34383774, 2021). "The World Health Organization (WHO) recommends that G6PD activity be measured before efforts to perform radical treatment of malaria." (PMID 33879156, 2021). "This is consistent with several studies in SE Asia of the FST and G6PD RDTs, demonstrating their high sensitivities in malaria patients and healthy individuals with enzyme activities < 30% activity with a spectrum of mostly WHO class II G6PD variants." (PMID 34495956, 2021). "Global health authorities and national malaria control programmes alike advise using primaquine to prevent relapse of latent malaria applying varying doses, dosing strategies, and G6PD precautions." (PMID 34270547, 2021). "The application of G6PD RDT in malaria patients allows for identification of vulnerable population with hemolytic potential, defined as less than 30% of enzyme activity, before primaquine treatment." (PMID 34108049, 2021).
malaria (continued). "Several factors such as the levels of G6PD enzyme activity, the method used to determine the deficiency and the small number of samples employed in previous studies could have resulted in the conflicting reports on the protection offered by G6PDd against malaria." (PMID 34570821, 2021). "The primary objective of this study was to evaluate the performance of the STANDARD G6PD Test as compared to a spectrophotometric reference assay in the detection of G6PD activity when used by trained health care workers in a malaria-endemic setting in Brazil." (PMID 34383774, 2021). "Brito-Sousa recently reported the challenges during a mass G6PD screening in the Brazilian amazon, it showed good acceptability by the population, making it viable to perform mass G6PD testing in endemic malaria regions in Brazil." (PMID 34174880, 2021). "In the context of malaria case management, the performance of the test among females with intermediate G6PD activity levels is of particular relevance due to the associated implications for both primaquine and Kozenis administration." (PMID 34383774, 2021). "In a survey conducted in periurban Manaus, in the Amazon region of Western Brazil, where P. vivax is now the predominant (90%) cause of malaria, there was also a very strong protective effect of G6PD Med against self-reported previous malaria (AOR: 0.010)." (PMID 33543710, 2021). "Widespread use of G6PD tests as part of malaria case management has been limited, in part due to due concerns regarding product usability, user training, and supervision." (PMID 34238299, 2021). "Currently, WHO recommends G6PD testing prior to PQ administration; however in most malaria-endemic countries PQ is withheld due to inability to test G6PD activity." (PMID 34899347, 2021). "In total, 7.7% (14/182) of patients with malaria had G6PD activity < 70% compared to 25.0% (248/992) of participants with submicroscopic or no parasitemia (odds ratio [OR] 0.25, 95% CI 0.14-0.44, p < 0.001)." (PMID 33891581, 2021). "When Methylene Blue (MB) was used against malaria, significant haemoglobin drops in A- G6PD hemizygous and homozygous children were shown in West Africa using the gametocytocidal dose (15 mg/Kg per day for 3 days) but with limited clinical impact." (PMID 33790795, 2021). "In the next several years, safe implementation of tafenoquine (with G6PD testing) in malaria-endemic settings for the efficacious prevention of relapse should be established at primary health-care levels by qualified health-care providers." (PMID 33306921, 2021). "We did not have a no primaquine arm which would have given us useful information on the effects of malaria itself and its treatment on the changes in G6PD activity and reticulocyte counts over time." (PMID 34495956, 2021). "The current WHO malaria treatment guidelines recommend that G6PD testing be conducted prior to prescription of primaquine." (PMID 34383774, 2021). "Genomic scans suggest that immunity genes such as AKT3 and IL13 (possibly involved in simian immunodeficiency virus defense), and G6PD, a gene involved in malaria resistance, are under positive natural selection." (PMID 32986826, 2021). "The Bangladesh National Malaria Elimination Programme (NMEP) is currently considering novel approaches to G6PD diagnostics, supported by a dynamic research programme." (PMID 33980257, 2021). "This study investigates end-user perspectives in Bangladesh on the introduction of a quantitative G6PD test (SD Biosensor STANDARDTM G6PD analyser) to support malaria elimination." (PMID 33980257, 2021). "The qualitative CareStart G6PD screening test was implemented in 12 malaria treatment units (MTUs) in the municipality of Rio Preto da Eva, Western Brazilian Amazon, a malaria endemic area, between February 2019 and early January 2020." (PMID 34003840, 2021). "Glucose-6-phosphate dehydrogenase (G6PD) deficiency is a common enzyme deficiency, prevalent in many malaria-endemic countries." (PMID 34383774, 2021).
malaria (continued). "Some of the primary concerns regarding the adoption of G6PD testing at the point of care and the integration of these tests into malaria case management centre around user training and supervision." (PMID 34238299, 2021). "Sub-analyses also explored the performance of the STANDARD G6PD Test by the malaria status of participants." (PMID 34383774, 2021). "This usability assessment was conducted in view of one specific use case for POC G6PD testing, malaria case management, and with a group of representative end users specific to this context of use." (PMID 34238299, 2021). "This study focuses on the performance of the STANDARD G6PD Test in a malaria-endemic clinical setting in Brazil, with the majority of the recruitment conducted in outpatient clinics." (PMID 34383774, 2021). "Where G6PD testing is driven by malaria case management, often rural and lower socioeconomic populations will benefit, as these populations often experience higher rates of malaria infection." (PMID 32766454, 2020). "PQ is not widely used in Cambodia due to unavailability of suitable G6PD screening tests, which negatively impacts the progress of malaria elimination in the region." (PMID 32004348, 2020). "The co-inheritance of Hb variations and G6PD variation are important predictors of malaria disease outcome in this region." (PMID 32646433, 2020). "New, affordable, point-of-care quantitative G6PD diagnostics have been developed to support access to these drugs in malaria-endemic populations." (PMID 32766454, 2020). "With approval from the AFMC IRB (AFMC-17-IRB-023), a POC-based G6PD activity test by venipuncture using the CareStart G6PD & Hb kit was performed for 1632 newly recruited soldiers at the Paju and Yangju training camps, where malaria is endemic." (PMID 32873296, 2020). "Some of the most well-known cases involve malaria resistance, driven by genes such as Glucose-6-phosphate dehydrogenase (G6PD) and the Duffy antigen protein." (PMID 33092534, 2020). "The combination of reliable G6PD testing combined with safe and effective 8-aminoquinoline regimes holds promise for the elimination of all malarias." (PMID 31900172, 2020). "The amount of blood required for the venous sampling in the case-control study to identify the levels of G6PD activity was considered problematic as a larger volume than a regular malaria diagnosis was collected." (PMID 33066621, 2020). "In practice, the DHC’s workload was often also too high to accommodate the request to perform microscopy for regular malaria diagnosis, let alone assist with additional tasks such as G6PD testing." (PMID 33396538, 2020). "Using a non-conditional model, a binary logistic regression, including covariant, anti-malaria drugs, MBL2 gene polymorphism, G6PD and parasitaemia, it was observed that MBL2*AB or AC is protective factor in the development of BWF." (PMID 31941497, 2020). "Considering the role of glucose-6-phosphate dehydrogenase (G6PD) in metabolism, this enzyme has been considered as a pharmacological target for some microorganisms, such as the protozoan that causes malaria Plasmodium falciparum." (PMID 32650494, 2020). "Because of the long half-life of tafenoquine, screening for G6PD must be done prior to giving the drug to malaria patient." (PMID 32552815, 2020). "There is considerable evidence to suggest that G6PD protects both male and female African children against severe malaria." (PMID 31941490, 2020). "Steps towards meeting the SDG include prevention of malaria in pregnancy, reducing unnecessary exclusion of women from radical cure, and accessible quantitative G6PD screening in P. vivax-endemic settings." (PMID 31969155, 2020). "Field-validated point-of-care quantitative G6PD tests are an urgent priority to meet the ambitious WHO target of reducing malaria by 90% by the year 2030." (PMID 31969155, 2020).
malaria (continued). "Decisions to include qualitative G6PD testing in clinical guidelines or use them as a matter of policy do provide broader access to G6PD testing and improve health disparities in malaria treatment." (PMID 32766454, 2020). "The successful rollout of tafenoquine will therefore require more stringent G6PD screening than is currently available in malaria endemic areas." (PMID 32407380, 2020). "The team conducted malaria and G6PD blood testing, and provided comprehensive malaria treatment (chloroquine and primaquine)." (PMID 32456698, 2020). "Our analysis provides reassuring evidence that, in an area with a high burden of malaria and low G6PD prevalence the beneficial effects of PQ outweigh its risks." (PMID 33175835, 2020). "Increasing access to G6PD screening will be important to reach the goal for eliminating Pv malaria from Cambodia by 2025." (PMID 32004348, 2020). "Daniel Pfeffer and coauthors report on the assessment of glucose-6-phosphate dehydrogenase activity, which is required for safe use of some malaria treatments." (PMID 32407380, 2020). "Some studies reported that G6PD protects both heterozygous females and hemizygous males from severe malaria, others reported protection for only hemizygous males, and others reported no protection." (PMID 31941490, 2020). "Further, co-inheritance of sickle cell and G6PD status are important predictors of malaria disease outcome." (PMID 32646433, 2020). "High incidence of uncomplicated malaria was observed in heterozygous females and hemizygous males with G6PD A− compared to participants with the wild-type genotype." (PMID 30819192, 2019). "G6PD variants were characterized in samples collected from Cambodia, Lao PDR, Myanmar, Thailand and Vietnam during National Malaria Program surveys (NMS) and population surveys (PS)." (PMID 30674319, 2019). "This knowledge gap has been extremely challenging to address operationally, especially in malaria-endemic settings, due to the complexity of performing quantitative G6PD testing." (PMID 30184203, 2019). "It is possible that malaria influences G6PD activity, although it is unlikely that this would have impacted the observed performance because CSG and spectrophotometry testing were done on the same sample." (PMID 31834890, 2019). "The gold standard method for measuring G6PD activity is quantitative spectrophotometry, but this method is expensive and requires laboratory facilities that are often unavailable in malaria-endemic communities, especially in remote areas." (PMID 31834890, 2019). "We found that all Bubi individuals possessed the malaria-resistant allele of the ACKR1 and CD36 genes, in addition to certain variations in other genes such as G6PD, ATP2B4, GRK5, and IL-10." (PMID 30841922, 2019). "If national malaria programs mandate daily primaquine dosing (the recommended regimen for G6PD normal individuals), then G6PD testing before prescription is necessary to avoid iatrogenic haemolysis in G6PD deficient individuals." (PMID 31069260, 2019). "Since Pv and mixed infections contribute to more than two-thirds of malaria in this setting, scaling up of G6PD testing is important." (PMID 31817078, 2019). "In order to eliminate vivax malaria, appropriate test-and-treatment strategies, including use of point-of-care quantitative G6PD tests, will need to be devised by the National Malaria Programmes for the safe and wide use of 8-aminoquinolines in the region." (PMID 30674319, 2019). "CDC recommended further treatment for malaria with primaquine after arrival, after glucose-6-phosphate dehydrogenase testing, to target liver-stage parasites." (PMID 30543602, 2018). "Test coverage is low due to the need to prioritize newborn interventions and the complexity of currently available G6PD tests, especially those used to inform malaria case management." (PMID 31709308, 2018).
malaria (continued). "Therefore, our findings might not represent the effect of single low-dose primaquine and methylene blue in other malaria-infected populations, particularly those with lower gametocyte densities who have lower pre-treatment and post-treatment transmission potential and G6PD-deficient populations." (PMID 29422384, 2018). "The presence of the A− variant alongside other G6PD mutants and the patchy distribution of G6PDd indicate that larger studies specifically designed to unravel the distribution of G6PDd at small geographical scale may be needed to tailor malaria elimination efforts in Ethiopia to the local context." (PMID 30071859, 2018). "The WHO malaria treatment guidelines address the 14-day course for preventing relapse with caution, including a statement that good practice requires that the G6PD status of patients should be ascertained prior to administration of PQ." (PMID 30071859, 2018). "In this study, G6PDd was investigated in different malaria endemic settings in the Ethiopian population using enzymatic assay and multiple allelic forms of G6PD were analysed by genotyping." (PMID 30071859, 2018). "This is an essential characteristic for malaria case management because patients are lost to follow-up if they are asked to return for their G6PD test result several days later." (PMID 31709308, 2018). "Because of this uncertainty, the World Health Organization (WHO) 2015 malaria treatment guidelines recommend delaying radical cure for lactating women until their nursing infants are at least 6 months old and determined to be G6PD normal." (PMID 29590311, 2018). "In malaria-endemic regions, G6PD testing will provide access to the best standard of care, which is a radical cure of P. vivax malaria." (PMID 31709308, 2018). "The MST intervention involved community-wide expert malaria microscopic screening and standard therapy with dihydroartemisinin-piperaquine and primaquine for glucose-6 phosphate dehydrogenase–normal subjects." (PMID 29579195, 2018). "For tafenoquine, this will require the use of a G6PD test that can quantify the G6PD activity, posing a significant challenge for malaria control programmes." (PMID 29677199, 2018). "Studies have included G6PDd and G6PD normal healthy individuals, malaria patients and asymptomatic P. falciparum carriers – all with high baseline Hb concentrations, usually ≥8 g/dL." (PMID 29347975, 2018). "A study investigating the safety of 0.25 and 0.40 mg/kg PQ in asymptomatic G6PD-d patients with malaria in Burkina Faso has been completed, although results have not yet been reported." (PMID 29342267, 2018). "Similar results were reported from a study done by G6PD fluorescent spot test among unrelated males of Karen (4.1%) and Burman (12.9%) ethnic groups in a malaria endemic region on the Thailand-Myanmar border and in five ethnic groups in Pakistan." (PMID 30918572, 2018). "Several countries have introduced routine screening for G6PDd in neonates and the current WHO malaria treatment guidelines recommend that where possible, G6PD testing should be undertaken prior to administration of primaquine for radical cure." (PMID 30388146, 2018). "Cost-effectiveness models for G6PD testing for a radical cure have been developed; however, these do not integrate the use of tests at birth to avoid complications, or beyond that, of malaria case management." (PMID 31709308, 2018). "It is therefore not surprising that all aspects of RBC, including the hemoglobin (S, C, E and thalassemia), membrane antigens (Duffy antigen, ovalocytosis and blood group O) and enzymes (G6PD) are involved in protection against malaria." (PMID 30204801, 2018). "None of the most specific mutations for malaria resistance, like those at G6PD, HBB or Duffy blood group, have been detected among the available samples, while many other malaria-resistant alleles existed well before the advent of agriculture." (PMID 28469196, 2017).